IGFBP2 (insulin like growth factor binding protein 2)
Diseases named in the same sentence as IGFBP2 in open-access papers (continued):
Sharing a sentence is not in itself a finding about the gene and the disease.
breast carcinoma (continued). "Furthermore, in comparisons between controls and each type of cancer, 5% of breast cancer patients (p = 0.032) and 40% of colorectal cancer patients (p < 0.001) had IGFBP-2 specific antibodies, compared to controls." (PMID 18510754, 2008). "We have recently established insulin-like growth factor binding protein (IGFBP-2) as a human tumor antigen found at elevated levels in colon and breast cancer patients, and in colon cancer patients IGFBP-2 overexpression is highly correlated with metastases and recurrence." (PMID 18510754, 2008). "In addition, the overexpression of IGFBP2 may be a feature of basal-like breast cancer that correlates with a low survival rate." (PMID 31296201, 2019). "This may be indicative of a dual role for IGFBP-2 in breast cancer development." (PMID 26106415, 2015). "However, mechanisms that govern IGFBP2 actions in breast cancers are poorly understood." (PMID 23767917, 2013). "In multiple experimental systems including primary mammary tumors, cultured human cells, and Brca1-deficient mice, Shukla and colleagues showed that BRCA1 deficiency resulted in increased expression of IRS1, IGF1R and IGFBP2, and increased levels of serum IGF1." (PMID 19843326, 2009). "This study aimed to further investigate the role of IGFBP-2 in the DNA damage response induced by etoposide in MCF-7, T47D (ER+ve), and MDA-MB-231 (ER-ve) breast cancer cell lines." (PMID 38893232, 2024). "In contrast, exogenously applied IGFBP2 has been reported to inhibit in vitro and in vivo tumor growth, which is in line with IGF-II inhibition suppressing the growth of breast cancer xenografts." (PMID 37436978, 2023). "IGFBP2 was identified as part of a screen for anti-invasive factors, where exogenous recombinant proteins were applied to invading MM231 breast cancer cells." (PMID 37436978, 2023). "Here, we found that IGFBP2 was able to bind and sequester IGF-II, which prevents the autocrine signaling of breast cancer cells and limits their progression toward invasive disease." (PMID 37436978, 2023). "Meta-analyses reveal that IGFBP2 and IGFBP3 both correlate positively with breast cancer and poor prognosis in patients." (PMID 34225729, 2021). "Other BPs such as IGFBP-1, IGFBP-2, and IGFBP-5 also play a role in breast cancer, but were outside the scope of this study." (PMID 33767994, 2021). "Since T2DM is characterized by hyperglycemia, the potential role of IGFBP2 in T2DM induced breast cancer, and particularly as a therapeutic target to increase chemo-sensitivity of breast cancer cells seems plausible." (PMID 34225729, 2021). "Indeed, the protease-resistant IGFBP2 inhibits MCF-7 human breast cancer cell proliferation in vitro, and when it is combined with a non-matrix-binding mutation, the IGFBP2 mutant more effectively inhibits the growth and angiogenesis of MCF-7 tumor xenograft in vivo." (PMID 32133294, 2020). "Insulin-like growth factor-binding protein 2 (IGFBP2), secreted by metastatic breast cancer cells, contributes to metastatic bone colonization by interacting with IGF type-1 receptor on endothelial cells through endothelial recruitment." (PMID 32674405, 2020). "Dysregulation of IGFBPs as a result of epigenetic modifications has been identified in many tumours, such as aberrant DNA methylation of the promoter of IGFBP-2 and IGFBP-3 genes in hepatomas and breast cancers respectively." (PMID 31903164, 2019). "Having shown that IGFBP-2 plays a role in hyperglycaemia-induced chemo-resistance, adding exogenous recombinant IGFBP-2 to breast cancer cells and monitoring their response to chemotherapy was performed to further investigate the effect of IGFBP-2 on survival." (PMID 29088813, 2017). "Having determined that glucose increased the levels of IGFBP-2 both at the protein and mRNA levels in breast cancer cells, the role of IGFBP-2 in the response of breast cancer cells to chemotherapy was investigated." (PMID 29088813, 2017).
breast carcinoma (continued). "Previous studies in our laboratory have shown that IGFBP-2 is a novel regulator of the ERα, and that FASN and ERα overexpression in hyperglycaemic conditions contributes to chemo-resistance in breast cancer cells." (PMID 29088813, 2017). "This is the first study to evaluate the relationship of tissue expression of IGF1, IGFR1, IGFBP2, and IGFBP3 and survival in US breast cancer patients of Asian, Pacific Islander, and Caucasian ancestry." (PMID 25619494, 2015). "It is currently not very clear how the adipocytes can selectively increase the secretion of IGFBP-2, and we only confirmed that the IGFBP-2 secreted from adipocytes was very important to the invasion ability of breast cancer cells." (PMID 25747684, 2015). "In breast cancer, the role of miR-126 in tumor metastasis may be related to the negative regulation of insulin receptor substrate-1 expression and it inhibits endothelial cell recruitment and angiogenesis through the negative regulation of IGFBP2/IGF1/IGF1R and GAS6/ MERTK signaling pathways." (PMID 24350576, 2013). "In estrogen-receptor-positive breast cancer cells, such IGF-1R-independent actions of IGFBP-2 were found to be dependent on the presence of ERα, as silencing ERα eliminated these intrinsic effects of IGFBP-2." (PMID 38893232, 2024). "Furthermore, adipocyte- or CAA-secreted factors, including leptin, TNF-α, IL-6, IL-1β, IGFBP-2, LCN2, collagen VI, and others, have also been demonstrated to promote breast cancer cell malignant progression, such as EMT, invasion, and metastasis." (PMID 32242230, 2020). "Since IGFBP-2 expression and secretion is increased in high glucose and IGFBP-2 has a role in inducing resistance to chemotherapy in breast cancer cells, this may suggest that IGFBP-2 might have an effect on P-gp, which would need to be investigated." (PMID 29088813, 2017). "In addition, another study revealed that the PI3K/AKT pathway promoted the expression of IGFBP2 in MCF-7 breast cancer cells, and LY294002 (a PI3K inhibitor) directly reduced IGFBP2 production via the SP-1, which is a transcription factor involved in IGFBP2." (PMID 28036255, 2017). "Within other types of cancer (e.g. prostate and breast cancer), the roles of IGFBP-3 and IGFBP-2 have been more thoroughly described, and demonstrated to convey both inhibitory and stimulating effects on tumor progression, depending on the tissue and type of cancer." (PMID 27111220, 2016). "While medium obtained from the co-cultures of IGFBP-2 knock-out breast cancer cells stimulated the invasion of breast cancer cells, co-culture medium from IGFBP-2 knock-out adipocytes did not induce cancer cell invasion." (PMID 25747684, 2015). "Although no studies have previously examined the association between IGFBP-2 and risk of BPBD, there is some epidemiological evidence for a role of IGFBP-2 in breast cancer." (PMID 26106415, 2015). "This is an interesting finding as it is generally considered that IGFBP2 is oncogenic in breast cancer; however, these other studies did not correct for factors such as BMI." (PMID 25774149, 2015). "We next aimed to determine the cellular origin and distribution of IGFBP-2 in metastatic and non-metastatic mammary tumor samples." (PMID 25747684, 2015). "In invasive (MCF-7/6) or in breast cancer cell lines adapted to low serum concentrations (MCF-7/S0.5) and in Fischer rat mammary adenocarcinoma cells, E2s suppressed intracellular and/or secreted levels of IGFBP-2." (PMID 24778626, 2014). "In order to establish Wnt pathway activation by IGFBP2, we examined the canonical Wnt signaling target, β-catenin in IGFBP2 knockdown breast cancer cells." (PMID 23767917, 2013). "In order to identify the genes commonly regulated by IGFBP2 in cell lines and tumors, we compared the gene expression profiles of IGFBP2 positive versus negative tumors and IGFBP2 knockdown breast cancer cells." (PMID 23767917, 2013).
breast carcinoma (continued). "Interestingly, in a previous report, expression of IGFBP2 and IGFBP5 were correlated with increased lymph node metastasis in T1 breast carcinoma." (PMID 23767917, 2013). "To further validate these results in breast cancer tissues, we performed whole genome expression analysis in 19 breast tumors which were categorized as IGFBP2 positive or negative based on immunohistochemical staining pattern." (PMID 23767917, 2013). "This study aimed to explore whether IGFBP-2 plays a role in the mechanism of DNA damage and repair in breast cancer cells and whether this is dependent or independent of interaction with IGFs." (PMID 38893232, 2024). "Breaching of the basement membrane is one of the first steps in breast cancer invasive progression, and when modeling this process using Matrigel invasion chambers, we again found a clear reduction in MM231 cell invasion in the presence of the anti–IGF-II function-blocking antibody and IGFBP2." (PMID 37436978, 2023). "There are similar results in the literature: IGFBP2 inhibits the proliferation of human breast cancer cell line Hs578T, which does not express IGFBP2, similarly to 4T1 (data not shown), suggesting that the pro- or anti-tumorigenic effect of IGFBP2 depends on the actual state of the cancer cell." (PMID 32133294, 2020). "Furthermore, we have previously shown that IGFBP‐2 in breast cancer cells was a marker of resistance to anti‐estrogen therapy, whereas cell proliferation did not depend on IGFBP‐2 expression." (PMID 29722920, 2018). "Interestingly, when not occupied by IGF‐II, IGFBP‐2 has been shown to suppress PTEN in breast cancer cells." (PMID 29722920, 2018). "In this study we have shown that glucose-induced IGFBP-2 secretion promoted resistance of breast cancer cells to chemotherapy; whether or not the RGD motif in IGFBP-2 is responsible for these actions is still unclear and needs further investigation." (PMID 29088813, 2017). "Human recombinant IGFBP2 activated the ERK signaling pathway and stimulated proliferation in glioblastoma cells (through an integrin β1-dependent mechanism) and ovarian cancer cells and was shown to increase ERK as well as AKT activation in breast cancer cells." (PMID 26317790, 2015). "Since IGFBP2 is itself a potential target for therapeutic intervention, and has been shown to inhibit the growth of breast cancer cells in vivo, we propose that since HDAC3 is involved in reducing expression of IGFBP2, HDAC inhibitors maybe a useful tool to treat patients with progressive disease." (PMID 26107517, 2015). "For all-cause and breast cancer-specific mortality, no heterogeneity of effects was observed by race/ethnicity for IGF1 (P for interaction 0.26 and 0.45, respectively), IGF1R (P for interaction 0.43 and 0.72), or IGFBP2 (P for interaction 0.49 and 0.32)." (PMID 25619494, 2015). "Hence, evaluation of IGFBP2, IGFBP5 along with β-catenin may provide a stronger predictive value for the prognosis of breast cancer." (PMID 23767917, 2013). "Though we cannot rule out the possibility that the association between IGFBP-2 and percent MD may be due to residual confounding by adiposity, both laboratory and epidemiologic studies have suggested an important role of IGFBP-2 in breast cancer etiology." (PMID 31337427, 2019). "However, because IGFBP-2 could create a microenvironment that is more favorable to invasion and metastasis through the up-regulation of MMP-2, the adipocytes may become a new target to reduce the extent of breast cancer metastasis." (PMID 25747684, 2015). "The positive correlation of DDR1 with IGF-IR and IGFBP2, but not with AKT, INSR or IGFBP5, was further confirmed in the TCGA breast cancer dataset." (PMID 26655502, 2016). "Across all cases, overall survival and breast cancer-specific survival, unadjusted for confounders, did not vary by expression of IGF1, IGF1R, IGFBP2, or IGFBP3." (PMID 25619494, 2015).
breast carcinoma (continued). "The presence of SP1 together with IL2 signaling regulators, IGFBP2, IMPDH2 and HTT in separate subnetworks that excludes RAC signaling component might indicate the presence of at least two non-redundant mechanisms in P-inter breast cancers that may determine patient outcomes." (PMID 26257336, 2015).
glioblastoma (70 papers, 2007 to 2026). The most malignant astrocytic tumor (WHO grade IV). "Within the last 5 years, efforts to stratify and optimise glioblastoma patients for predicted responses to therapy by Yin, Prasad, Yu and colleagues independently identified IGFBP-2 in gene signatures (with under 20 genes) associated with worse outcomes." (PMID 40429889, 2025). "Of note, the overexpression of insulin-like growth factor binding protein 2 (IGFBP-2) in glioblastoma tumour tissue has been repeatedly reported and is associated with shorter patient survival." (PMID 40429889, 2025). "IGFBP2 overexpression occurs in advanced cancers, including ovarian cancer, prostate cancer, and glioblastoma, and its high expression has been linked to an aggressive phenotype." (PMID 39007351, 2024). "Univariate Kaplan Meier and Cox proportional hazards analysis of associations between OS, clinical covariates and GRP78/ IGFBP‐2 IHC protein expression of IDH1‐wildtype glioblastoma (n = 92)." (PMID 37212470, 2023). "Univariate Kaplan–Meier and Cox proportional hazards of associations between OS, and combinations of IGFBP‐2/GRP78 IHC protein expression of IDH1‐wildtype glioblastoma (n = 92)." (PMID 37212470, 2023). "A scFv has also been developed against the insulin-like growth factor binding protein 2 (IGFBP2), known to be overexpressed in glioblastoma and associated with increased cellular migration and invasion." (PMID 36077739, 2022). "Overexpressed in glioblastoma, IGFBP2 has previously been associated with promoting cell migration and invasion through binding α5β1 integrin, and activating NFκB mediated migratory phenotypes." (PMID 36430641, 2022). "IGFBP2 inhibits expression of E-cadherin in colorectal cancer and promotes immunosuppression associated with its mesenchymal induction in glioblastoma." (PMID 33473258, 2020). "IGFBP-2 has been linked to Hedgehog signal activation expression in glioblastoma, prostate, breast, and hematopoietic tumors." (PMID 28977895, 2017). "IGFBP2 is associated with increased cellular proliferation, migration, and invasion in glioblastomas." (PMID 28786923, 2017). "The low expression of IGFBP2 observed in some glioblastoma cell lines, is associated with methylation of the IGFBP2 promoter and can be restored with 5-azacytadine treatment suggesting regulation by DNA methyltransferase 1 (DNMT1)." (PMID 25774149, 2015). "Interestingly, IGFBP2 expression was shown to promote neural stem cell maintenance and proliferation, and was associated with differences in glioblastoma subtypes." (PMID 37737709, 2023). "A reduction of IGFBP-2 was correlated with the promotion of epithelial invasion in the progression of cervical cancer, and loss of IGFBP-2 was also found at the invasive front of glioblastoma with high 8, line grade suggesting that IGFBP-2 is associated with a less aggressive phenotype." (PMID 31903164, 2019). "However, this advantage reduced by half and lost statistical significance when the only 7 IDH-mutant cases were subtracted from the analysis, further supporting an intimate relationship between IDH mutations and IGFBP2 in glioblastoma prognosis." (PMID 27852048, 2017). "However, high levels of IGFBP2 are also linked with resistance to other therapeutics and high levels of IGFBP2 following radio/chemotherapy also correlate with poor survival in elderly patients with glioblastoma." (PMID 25774149, 2015). "A manual survey of the GeneCards database and the literature on glioblastoma revealed that both clusters were characterized by some genes involved in cancer (e.g. H19 for C.L.1 and IGFBP2 for C.L.L.L)." (PMID 40491972, 2025). "In efforts to rationalise this prognostic effect, in vitro glioblastoma studies suggest that IGFBP-2 frequently functions independently of insulin-like growth factor (IGF) signalling." (PMID 40429889, 2025).
glioblastoma (continued). "Many mechanistic studies of IGFBP-2 thus far have been carried out in immortalised glioblastoma cell lines such as U251, U87 and T98G due to their ease of use and relatively low cost to maintain." (PMID 40429889, 2025). "Insulin-like growth factor binding protein 2 (IGFBP-2) has a well-established prognostic role in glioblastoma, and cell-based mechanistic studies show the independent activation of downstream oncogenic pathways." (PMID 40429889, 2025). "Despite a wealth of research that indicates that IGFBP-2 exhibits oncogenic properties within glioblastoma, the specific effect of IGFBP-2 on the stem cell compartment (NSCs and GSCs) is sparse." (PMID 40429889, 2025). "Elevated IGFBP-2 levels are often seen in cancers such as glioblastoma, prostate cancer, and ovarian cancer, where they contribute to increased metastasis and aggressiveness." (PMID 39585162, 2024). "In glioblastoma and prostate cancer, IGFBP2 expression is negatively regulated by Phosphatase and Tensin homolog (PTEN) and positively correlated with AKR mouse thymoma kinase (AKT) expression." (PMID 39007351, 2024). "High levels of IGFBP2 correlate with proliferation, epithelial-to-mesenchymal transition, invasion, and reduction of cell death in glioblastoma, prostate cancer, breast cancer, and melanoma." (PMID 39007351, 2024). "Associations between GRP78 or IGFBP‐2 IHC protein expression and clinicopathological features of IDH1‐wildtype glioblastoma (n = 92)." (PMID 37212470, 2023). "Clinicopathological variables and covariates for 9 patients with a high IGFBP‐2/low GRP78 IHC protein expression in a cohort of 92 patients with IDH1‐wildtype glioblastoma." (PMID 37212470, 2023). "We quantified GRP78 and IGFBP‐2 protein expression for 92 IDH‐wildtype glioblastoma patient tumour samples." (PMID 37212470, 2023). "Previous studies have identified insulin‐like growth factor binding protein‐2 (IGFBP‐2) as a potential biomarker for glioblastoma diagnosis and therapeutic targeting." (PMID 37212470, 2023). "In glioblastoma, IGFBP2 correlates with an increase of M2 macrophages and a decrease of B cells and cytotoxicity T cells." (PMID 36556226, 2022). "Overexpression of IGFBP2 gene is observed in many neoplastic diseases including glioblastoma multiforme." (PMID 35454784, 2022). "It has also been shown that increased levels of IGFBP2 mRNA can anticipate an unfavorable survival status in patients with glioblastoma." (PMID 35989938, 2022). "Reduction in the production or neutralisation of IGFBP2 by the glioblastoma cells is therefore an attractive consideration." (PMID 36430641, 2022). "IGFBP2 has been suggested as a potential biomarker for glioblastoma, prostate cancer, colorectal cancer, and lupus nephritis." (PMID 34054689, 2021). "In the present study, RNAscope probe was used to detect the expression of IGFBP2 mRNA in 180 glioblastomas." (PMID 31296788, 2019). "For glioblastoma IGFBP2, EGFR_pY1068, HER2_pY1248, Caveolin-1, Akt_pT308, Fibronectin, Collagen_VI, and EGFR_pY1173 are decreased in the group of mutated cases." (PMID 30442178, 2018). "In our predictions, removing the feedback from IGFBP2 to HIF1α resulted in almost half of the growth in the glioblastoma diameter over 40 days as compared to removing the downstream signal from IGFI to HIF1α." (PMID 25884993, 2015). "Results of the model suggest a novel observation: feedback from IGFBP2 to HIF1α is integral to the sustained growth of glioblastoma." (PMID 25884993, 2015). "While other researchers have highlighted the importance of IGFBP2 in glioblastoma growth, we have been able to suggest a specific mechanism that can be potentially targeted." (PMID 25884993, 2015).